RNU6-851P (RNA, U6 small nuclear 851, pseudogene)
Gene: Small nuclear RNA gene on chromosome 2 (38,884,560 to 38,884,666, reverse strand). Ensembl gene ENSG00000207295.
Homologues: Orthologues: chimpanzee U6 (100% identical), macaque U6 (92% identical), pig U6 (79% identical). Paralogues in human: RNU6-16P (85% identical), RNU6-444P (85% identical), RNU6-797P (85% identical), RNU6-1083P (84% identical), RNU6-1124P (84% identical), RNU6-1152P (84% identical), RNU6-11P (84% identical), RNU6-24P (84% identical), RNU6-301P (84% identical), RNU6-35P (84% identical), RNU6-37P (84% identical), RNU6-43P (84% identical), and 1284 more.